RNU2-38P (RNA, U2 small nuclear 38, pseudogene)
Gene: Small nuclear RNA gene on chromosome 1 (148,939,739 to 148,939,817, reverse strand). Ensembl gene ENSG00000222788.
Homologues: Orthologues: rabbit U2 (76% identical), dog U2 (75% identical). Paralogues in human: U2 (100% identical), U2 (80% identical), RNU2-2 (78% identical), U2 (78% identical), RNU2-6P (77% identical), RNU2-17P (76% identical), RNU2-28P (76% identical), RNU2-4P (76% identical), RNU2-59P (76% identical), U2 (76% identical), RNU2-32P (75% identical), RNU2-3P (75% identical), and 66 more.